DCTPP1 (dCTP pyrophosphatase 1)
Description:
Hydrolyzes deoxynucleoside triphosphates (dNTPs) to the corresponding nucleoside monophosphates. Has a strong preference for dCTP and its analogs including 5-iodo-dCTP and 5-methyl-dCTP for which it may even have a higher efficiency. May protect DNA or RNA against the incorporation of these genotoxic nucleotide analogs through their catabolism.
Synonyms: XTP3TPA; CDA03; MGC5627; RS21C6
Tractability: Small molecule: a structure with a bound ligand is known; a high-quality ligand is known. PROTAC: ubiquitination databases record sites on it; its protein half-life has been measured; a small molecule that binds it is known.
Target class: Enzyme; Hydrolase
Chemical probes: ZINC4511851 (high quality)
Gene: Protein-coding gene on chromosome 16 (30,423,615 to 30,430,030, reverse strand). Ensembl gene ENSG00000179958.
Subcellular location: Mitochondrion; Nucleus; Cytoplasm, cytosol
Subcellular location (Human Protein Atlas): Cytosol; Nucleoplasm
Pathways (Reactome):
Metabolism: Interconversion of nucleotide di- and triphosphates
Gene Ontology:
Molecular function: dCTP diphosphatase activity; identical protein binding; nucleoside triphosphate diphosphatase activity; protein binding; magnesium ion binding; pyrimidine deoxyribonucleotide binding; pyrophosphatase activity
Biological process: dCTP catabolic process; DNA protection; dTTP catabolic process; nucleoside triphosphate catabolic process
Cellular component: cytosol; mitochondrion; nucleoplasm; nucleus
Genetic constraint (gnomAD): Loss-of-function variants: 12 observed, 13.3 expected, observed/expected ratio (o/e) 0.9, 90% interval 0.58 to 1.46. The upper end of that interval is the gene's LOEUF score, 1.46, which puts it in group 6 of 6, group 1 being the genes least tolerant of losing a copy. Missense variants: 231 observed, 237.39 expected, observed/expected ratio (o/e) 0.97, 90% interval 0.87 to 1.09. Synonymous variants: 85 observed, 95.44 expected, observed/expected ratio (o/e) 0.89, 90% interval 0.75 to 1.07.
Homologues: Orthologues: chimpanzee DCTPP1 (99% identical), macaque DCTPP1 (98% identical), dog DCTPP1 (82% identical), pig DCTPP1 (82% identical), rabbit DCTPP1 (81% identical), guinea pig DCTPP1 (79% identical), mouse Dctpp1 (76% identical), rat Dctpp1 (64% identical), tropical clawed frog dctpp1 (48% identical), zebrafish dctpp1 (48% identical).
Diseases named in the same sentence as DCTPP1 in open-access papers:
DCTPP1 is named in the same sentence as 17 diseases in open-access papers, as found by Europe PMC text mining. Sharing a sentence is not in itself a finding about the gene and the disease. The quoted sentences say what the papers report.
breast carcinoma (8 papers, 2015 to 2025). "This substrate preference was also proved in breast cancer cells that the intracellular 5-methyl-dCTP level increased in DCTPP1-deficient MCF-7 cells but decreased in DCTPP1-overexpressed MDA-MB-231 cells." (PMID 26075750, 2015). "In the present study, we have confirmed our previous study that DCTPP1 was significantly hyperexpressed in breast cancer and further demonstrated its strong association with tumor progression and poor prognosis in breast cancer." (PMID 26075750, 2015). "DCTPP1 is an oncogene regulated by the oncogenic factor miR-378a-3p, and this gene facilitates breast cancer cell proliferation through the interference of DNA repair signaling pathway." (PMID 36267313, 2022). "What's more, high expression of DCTPP1 was strongly correlated with a poor prognosis in breast cancer and GC." (PMID 27612427, 2016). "By using tissue microarrays, 161 breast cancer tissues and 132 paired adjacent tissues were conducted for the determination of DCTPP1 expression." (PMID 26075750, 2015). "We also constructed DCTPP1 stably overexpressed breast cancer cell line MDA-MB-231, which expressed low level of DCTPP1 originally." (PMID 26075750, 2015). "On the basis of our previous work, we further verified the expression profiling of DCTPP1 in breast cancer here." (PMID 26075750, 2015). "Correlation between DCTPP1 expression and clinicopathological parameters was further analyzed in 161 cases of breast cancers." (PMID 26075750, 2015). "Our current investigations point to the pathological functions of DCTPP1 overexpression in breast cancer cells with aberrant dCTP metabolism and epigenetic modification." (PMID 26075750, 2015). "Our findings demonstrated that human DCTPP1 was involved in promoting breast cancer cell proliferation and stemness maintenance, largely through controlling 5-methyl-dCTP metabolism and global DNA hypomethylation." (PMID 26075750, 2015). "Knockdown of DCTPP1 in breast cancer cell line MCF-7 cells remarkably retarded proliferation and colony formation in vitro." (PMID 26075750, 2015). "We have verified the elevated expression of DCTPP1 in breast cancer." (PMID 26075750, 2015). "The intracellular 5-methyl-dCTP concentration increased in DCTPP1-knockdown breast cancer cell MCF-7, suggesting 5-methyl-dCTP is one of the main substrates of DCTPP1 in cells." (PMID 27612427, 2016). "In addition to this, several target proteins that have been shown to interact with TP are mostly highly expressed in breast cancer cells, such as XPB, TAB1, ADAM10, DCTPP1, Erα." (PMID 40444046, 2025). "By increasing DCTPP1, lncRNA DSCAM-AS1 plays an important role in the development of breast cancer." (PMID 36375472, 2022). "Here, the metabolic function of DCTPP1 was studied by using two different reverse genetics approaches, transient gene silencing and CRISPR/Cas9-based gene targeting, in two established mammalian cell models: breast cancer MCF-7 cells and the KBM-7-derived HAP1 cell line, respectively." (PMID 31377845, 2020).
gastric cancer (4 papers, 2014 to 2022). A primary or metastatic malignant neoplasm involving the stomach. "Through the cell models, we have observed that DCTPP1 is a promoter for the growth of ovarian cancer, which is consistent with the finding in prostate cancer and gastric cancer." (PMID 35223993, 2022). "DCTPP1 attenuates the sensitivity of human gastric cancer cells to 5-fluorouracil by up-regulating MDR1 expression epigenetically and DCTPP1 is involved in the cellular response to decitabine." (PMID 35223993, 2022). "RBBP6, DCTPP1, HSPA4, and ALDOA expression in particular were significantly associated with a poor prognosis in the 300 gastric cancer patients." (PMID 25379943, 2014). "Following univariate analysis, RBBP6, DCTPP1, HSPA4, and ALDOA expression levels were significantly associated with poor prognosis in 300 gastric cancer patients." (PMID 25379943, 2014). "RBBP6, DCTPP1, and HSPA9 were observed to be primarily expressed in the cytoplasm and nuclei of gastric cancer cells." (PMID 25379943, 2014). "In fact, with the elevated expression of DCTPP1 in cancerous regions, we also observed the hypomethylation in tumor tissues of gastric cancer (data not shown)." (PMID 26075750, 2015).
prostate carcinoma (4 papers, 2020 to 2024). A carcinoma that arises from epithelial cells of the prostate gland. "For example, higher expression of DCTPP1 is closely related to the worse prognosis of patients with BC and prostate cancer." (PMID 38753091, 2024). "Overexpression of DCTPP1 has been also described in multiple tumors and has been identified as a poor prognosis marker in gastric, breast and prostate cancer." (PMID 31377845, 2020).
ovarian carcinoma (3 papers, 2022 to 2025). A malignant neoplasm originating from the surface ovarian epithelium. "Our bioinformatics analysis confirmed that DCTPP1 is significantly overexpressed in ovarian cancer and is closely associated with tumour progression and poor prognosis after cisplatin treatment." (PMID 38686496, 2024). "DCTPP1 knockdown might cause more oxidative stress in ovarian cancer cells under cisplatin treatment." (PMID 35223993, 2022). "High expression of DCTPP1 is associated with malignancy of ovarian cancer, and its expression could be induced by cisplatin." (PMID 35223993, 2022). "Knocking out DCTPP1 reversed the drug resistance of ovarian cancer cells by enhancing the intracellular antioxidant stress response and accumulating ROS." (PMID 38686496, 2024). "Using publicly available databases, we analysed the expression and clinical significance of DCTPP1 in ovarian cancer." (PMID 38686496, 2024). "The screening and use of inhibitors targeting the enzymatic activity of DCTPP1 will enable a more in‐depth exploration of its role in cisplatin resistance in ovarian cancer (OC) and the potential of it serving as a cisplatin treatment enhancer." (PMID 38686496, 2024). "While this study provides valuable insights into the role of DCTPP1 in ovarian cancer (OC), there are still some limitations." (PMID 38686496, 2024). "In the following experiments, we demonstrated that the sensitivity of ovarian cancer cells to cisplatin can be increased by inhibiting DCTPP1." (PMID 35223993, 2022). "Both assays showed that DCTPP1 knockdown inhanced cisplatin sensitivity of ovarian cancer cells in both OVCAR8 and SKOV3 cells." (PMID 35223993, 2022). "This study aimed to identify the role of DCTPP1 in oxidative stress and cisplatin response of ovarian cancer." (PMID 35223993, 2022). "In this study, we verified that oxidative damage induced by cisplatin is the main factor of cytotoxicity, and then observed that cisplatin up-regulates the expression of DCTPP1 by generating ROS in ovarian cancer cells." (PMID 35223993, 2022). "DCTPP1 knockdown increases the sensitivity of ovarian cancer cells to cisplatin in cisplatin-sensitive cells, which is reflected in growth inhibition, increased levels of apoptosis and increased DNA damage." (PMID 35223993, 2022). "First, we used lentivirus to deliver shRNA targeting DCTPP1 to construct the DCTPPI knockdown cell model of ovarian cancer cells." (PMID 35223993, 2022). "To reveal the effect of DCTPP1 knockdown on intracellular ROS generation, we detected the total ROS levels in ovarian cancer cells using DHE staining." (PMID 35223993, 2022). "Based on our research findings, we conclude that DCTPP1 has prognostic value for ovarian cancer patients, and targeting DCTPP1 may be clinically significant in overcoming cisplatin resistance in ovarian cancer." (PMID 38686496, 2024). "Therefore, we cannot be sure that DCTPP1 knockdown can directly increase the level of intracellar ROS in ovarian cancer cells." (PMID 35223993, 2022). "With DCTPP1 knockdown, ovarian cancer cells showed growth inhibition both in vivo and in vitro." (PMID 35223993, 2022). "We hypothesized that DCTPP1 promotes resistance of ovarian cancer cells to cisplatin-induced intracellular ROS production." (PMID 35223993, 2022). "DCTPP1 knockdwon might enhence the cisplatin sensitivity of ovarian cancer cells and might be a promising therapeutic strategy." (PMID 35223993, 2022). "While, the responses of the two ovarian cancer cells were inconsistent after knockdown of DCTPP1." (PMID 35223993, 2022). "We tend to think that DCTPP1 may act as a redox-protected protein to help ovarian cancer cells respond to cisplatin-induced changes in intracellular ROS." (PMID 35223993, 2022). "Our data proposes that the development of therapeutic approaches targeting DCTPP1 may be useful in the treatment of ovarian cancer." (PMID 35223993, 2022).
ovarian carcinoma (continued). "However, the role of DCTPP1 in response to cisplatin in ovarian cancer cells remains largely unknown." (PMID 35223993, 2022). "Therefore, we speculate that cisplatin stimulates the overexpression of DCTPP1 in ovarian cancer cells to stabilize the accumulation of ROS in the cells, thereby protecting the cells from oxidative damage induced by cisplatin." (PMID 35223993, 2022).
cervical carcinoma (2 papers, 2020 to 2021). A carcinoma arising from either the exocervical squamous epithelium or the endocervical glandular epithelium. "Other studies suggest that DCTPP1 promotes 5-fluorouracil and decitabine resistance in stomach and cervical cancers." (PMID 32716908, 2020). "In addition, DCTPP1 was found to be differentially expressed in normal and cancerous tissues and it was significantly accumulated in the nucleus of cervical carcinoma, implying the important role of DCTPP1 under malignant pathology." (PMID 34149809, 2021).
Myocardial fibrosis (2 papers, 2023). "For DCTPP1 and GFRA1, a PubMed search did not identify any publications linking either protein with HDL-C, myocardial fibrosis, or myocardial scarring." (PMID 37790448, 2023).
pancreatic cancer (2 papers, 2019 to 2026). "DCTPP1 was expressed in 50 out of 60 pancreatic cancer cores, mainly in tumour cells that displayed mostly nuclear localization but also in cells in the tumour microenvironment, where DCTPP1 was localized in both the cytoplasm and nucleus." (PMID 31113993, 2019).
lung carcinoma (1 paper, 2025). "The “new” autoantibodies in our panel target TAAs like DCTPP1, GIMAP4, WWP2, MGMT, KCMF1, and GDA, which have demonstrated links to lung cancer pathogenesis." (PMID 39661479, 2025).
metastatic tumors (1 paper, 2024). "The primary tumors showed the highest frequency of DCTPP1 alterations, predominantly amplifications and gains, while recurrent and metastatic tumors displayed fewer alterations." (PMID 39200195, 2024).
mitochondrial DNA depletion syndrome (1 paper, 2026). The mitochondrial DNA (mtDNA) depletion syndrome (MDS) is a clinically heterogeneous group of mitochondrial disorders characterized by a reduction of the mtDNA copy number in affected tissues without mutations or rearrangements in the mtDNA. "DCTPP1 may therefore represent a promising therapeutic target for mitochondrial DNA depletion syndromes such as MNGIE." (PMID 41888522, 2026).
neuroblastoma (1 paper, 2020). Neuroblastoma (NB) is the most common solid, extracranial childhood tumor. "Interestingly, six genes ARMC6, DCTPP1, EIF4G1, ELOVL6, FBL and PRMT1 were associated with the clinical overall survival of neuroblastoma in both TARGET and GSE85047 datasets." (PMID 32593299, 2020). "The present study suggested new prognostic markers of ARMC6, DCTPP1, EIF4G1, ELOVL6 and FBL in neuroblastoma and highlighted the combinational prognostic significance of MYCN amplification and EIF4G1 expression in patients with neuroblastoma." (PMID 32593299, 2020). "Therefore, functions and prognosis of ARMC6, DCTPP1, EIF4G1, ELOVL6 and FBL in neuroblastoma should be further studied." (PMID 32593299, 2020). "However, the functions and prognosis of ARMC6, DCTPP1, EIF4G1, ELOVL6 and FBL in neuroblastoma were not reported." (PMID 32593299, 2020).
triple-negative breast carcinoma (1 paper, 2024). An invasive breast carcinoma which is negative for expression of estrogen receptor (ER), progesterone receptor (PR), and human epidermal growth factor receptor 2 (HER2). "Notably, the quantification of DCTPP1 expression in cell lines after the exposure to chemotherapeutic compounds corroborated these findings, showing higher DCTPP1 levels in luminal A cell lines compared to triple-negative breast cancer (TNBC)." (PMID 39200195, 2024).
cancer (16 papers, 2014 to 2025). A tumor composed of atypical neoplastic, often pleomorphic cells that invade other tissues. "DCTPP1 is highly expressed in various cancers and its elevated expression is associated with poor prognosis in various cancers." (PMID 40849295, 2025). "DCTPP1, a nucleoside triphosphate catabolizing enzyme, has been implicated in cancer development through nuclear accumulation, promotion of cancer stemness, and enhancement of cell proliferation." (PMID 39661479, 2025). "Overexpression of DCTPP1 has been linked to enhanced DNA repair capabilities, which can allow cancer cells to survive chemotherapy-induced DNA damage." (PMID 39200195, 2024). "DCTPP1, involved in nucleotide metabolism and maintenance of genomic stability, has been linked to cancer cell proliferation, survival, and drug resistance." (PMID 39200195, 2024). "A recently discovered enzyme called dCTP pyrophosphatase 1 (DCTPP1) has been implicated in regulating cancer characteristics, including drug responses." (PMID 38686496, 2024). "Human all-alpha dCTP pyrophosphatase 1 (DCTPP1) is implicated in numerous diseases, including cancers." (PMID 34113564, 2021). "In this study, we aimed to understand the role of DCTPP1 in cancer progression and cisplatin response." (PMID 38686496, 2024). "To further elucidate the DCTPP1 up-regulation in several cancer types, we examined its genetic alteration frequency across different tumors using data from the TCGA database, retrieved via cBioPortal." (PMID 39200195, 2024). "In ovarian cancer, DCTPP1 has been shown to mitigate the cytotoxic effects of cisplatin by reducing reactive oxygen species (ROS) accumulation, thereby protecting cancer cells from oxidative stress-induced apoptosis." (PMID 39200195, 2024). "Prior studies have indicated that DCTPP1 is upregulated in specific cancer types and correlates with enhanced proliferation and invasion capabilities of tumor cells." (PMID 38753091, 2024). "Several studies have reported that DCTPP1 is overexpressed in various cancers, emphasizing its role as an oncogene." (PMID 39200195, 2024). "This web tool corroborated the up-regulation of DCTPP1 in a majority of the cancers highlighted by TIMER2.0." (PMID 39200195, 2024). "Human deoxycytidine triphosphate pyrophosphatase 1 (DCTPP1) has emerged as a key player in various cancers, including BRCA." (PMID 39200195, 2024). "In summary, these analyses demonstrated a notable up-regulation of DCTPP1 in several types of carcinomas." (PMID 39200195, 2024). "The data provided by TIMER2.0 indicated a notable up-regulation of DCTPP1 in several types of carcinomas." (PMID 39200195, 2024). "Previous studies on DCTPP1’s effect on cancer are rare; however, these studies consistently suggest that DCTPP1 promotes the progression of some cancers." (PMID 32716908, 2020). "As DSCAM-AS1 positively regulated both DCTPP1 and QPRT, the DSCAM-AS1 deficiency probably conferred a cancer-inhibitory effect, such as knocking down both DCTPP1 and QPRT." (PMID 32716908, 2020). "Our previous study showed that DCTPP1 was highly expressed in multiple carcinomas and exhibited nucleic accumulation in cancer cells, including GC." (PMID 27612427, 2016). "On the basis of our findings, we conclude that DCTPP1 acts as an intracellular modulator for 5-methyl-dCTP metabolism and global hypomethylation, which is engaged in promoting cancer cell proliferation and stemness properties." (PMID 26075750, 2015). "Additionally, we found that DCTPP1 expression was only enhanced in SKOV3/S cells when treated with cisplatin, indicating different expression patterns of DCTPP1 in cisplatin‐sensitive and cisplatin‐resistant cancer cells." (PMID 38686496, 2024). "The positive correlations observed suggested that DCTPP1’s role in cancer biology may be intertwined with fundamental pathways governing tumor progression and hormone receptor signaling." (PMID 39200195, 2024).